VPS35L (VPS35 endosomal protein sorting factor like)
Description:
Acts as a component of the retriever complex. The retriever complex is a heterotrimeric complex related to retromer cargo-selective complex (CSC) and essential for retromer-independent retrieval and recycling of numerous cargos such as integrin alpha-5/beta-1 (ITGA5:ITGB1). The recruitment of the retriever complex to the endosomal membrane involves CCC and WASH complexes. In the endosomes, drives the retrieval and recycling of NxxY-motif-containing cargo proteins by coupling to SNX17, a cargo essential for the homeostatic maintenance of numerous cell surface proteins associated with processes that include cell migration, cell adhesion, nutrient supply and cell signaling. Involved in copper-dependent ATP7A trafficking between the trans-Golgi network and vesicles in the cell periphery; the function is proposed to depend on its association with the CCC complex and cooperation with the WASH complex on early endosomes. Does not seem to be required for CCC complex stability. (Microbial infection) The heterotrimeric retriever complex, in collaboration with the CCC complex, mediates the exit of human papillomavirus to the cell surface.
Synonyms: C16orf62; MGC16824; EC97; RTSC3
Tractability: Antibody: its Gene Ontology location is reachable by antibodies, with high confidence; UniProt predicts a signal peptide or a membrane-spanning region. PROTAC: ubiquitination databases record sites on it.
Gene: Protein-coding gene on chromosome 16 (19,555,240 to 19,706,793, forward strand). Ensembl gene ENSG00000103544.
Subcellular location: Membrane; Endosome
Subcellular location (Human Protein Atlas): Mitochondria
Pathways (Reactome):
Immune System: Neutrophil degranulation
Gene Ontology:
Molecular function: protein binding
Biological process: endocytic recycling; Golgi to plasma membrane transport
Cellular component: endosome; protein-containing complex; endoplasmic reticulum membrane; endosome membrane; ficolin-1-rich granule membrane; plasma membrane; membrane
Genetic constraint (gnomAD): Loss-of-function variants: 56 observed, 92.4 expected, observed/expected ratio (o/e) 0.61, 90% interval 0.49 to 0.76. The upper end of that interval is the gene's LOEUF score, 0.76, which puts it in group 3 of 6, group 1 being the genes least tolerant of losing a copy. Missense variants: 882 observed, 1,015.9 expected, observed/expected ratio (o/e) 0.87, 90% interval 0.82 to 0.92. Synonymous variants: 357 observed, 392.71 expected, observed/expected ratio (o/e) 0.91, 90% interval 0.83 to 0.99.
Homologues: Orthologues: chimpanzee VPS35L (99% identical), macaque VPS35L (99% identical), dog VPS35L (96% identical), rat Vps35l (94% identical), mouse Vps35l (94% identical), rabbit VPS35L (94% identical), guinea pig VPS35L (93% identical), tropical clawed frog vps35l (83% identical), zebrafish vps35l (74% identical), pig VPS35L (73% identical), Drosophila melanogaster CG8202 (42% identical), Caenorhabditis elegans F26G1.1 (22% identical).
Diseases named in the same sentence as VPS35L in open-access papers:
VPS35L is named in the same sentence as 10 diseases in open-access papers, as found by Europe PMC text mining. Sharing a sentence is not in itself a finding about the gene and the disease. The quoted sentences say what the papers report.
Ritscher-Schinzel syndrome (3 papers, 2023 to 2024). "The Retriever subunit VPS35L is the third responsible gene for Ritscher-Schinzel syndrome (RSS) after WASHC5 and CCDC22." (PMID 36113987, 2023). "Ritscher-Schinzel syndrome is a developmental disorder characterized by abnormal craniofacial, cerebellar, and cardiovascular malformations, classically associated with WASHC5 and CCDC22 but more recently with VPS35L and DPYSL5 being implicated as well." (PMID 39282277, 2024). "For example, and unsurprisingly given how the syndrome is defined, Ritscher-Schinzel syndrome genes CCDC22 and VPS35L shared highly similar phenotypes." (PMID 39282277, 2024).
hypercholesterolaemia (2 papers, 2023). "This likely describes the underlying molecular mechanism of hypercholesterolaemia present in these cases of VPS35L-associated RSS." (PMID 36113987, 2023). "In addition to typical features of RSS, we confirmed hypercholesterolaemia, hypogammaglobulinaemia and intestinal lymphangiectasia as novel complications of VPS35L-associated RSS." (PMID 36113987, 2023). "VPS35L-associated RSS is a distinct clinical entity with diverse phenotype and severity, with a possible molecular mechanism of hypercholesterolaemia." (PMID 36113987, 2023).
liver cancer (1 paper, 2023). An epithelial or non-epithelial malignant neoplasm that arises from the liver. "For this, we used CRISPR/Cas9 mediated gene editing to knock out VPS35L from liver cancer Huh-7 cells and then stably reconstituted VPS35L expression using an empty vector (EV), or VPS35L variants, including wild-type (WT), W6D, S829E, G902E, and G325E." (PMID 37397996, 2023).
cancer (2 papers, 2023). A tumor composed of atypical neoplastic, often pleomorphic cells that invade other tissues. "We found that mutations predicted to disrupt the interaction between the NT “belt” and the CT region of VPS35L, including W6D, S829E, and the cancer-derived mutation G902E, abolished the binding to VPS29 without affecting VPS26C binding." (PMID 37397996, 2023). "The specific effects of structure-guided and cancer-associated mutations in VPS35L allowed us to examine the physiological function of Retriever assembly in cell models." (PMID 37397996, 2023). "One key observation reported here is that cancer-associated missense mutations in VPS35L can dramatically affect Retriever assembly." (PMID 37397996, 2023). "It is remarkable that various VPS35L mutants, particularly the cancer-associated ones (G902E and G325E), recapitulated many of the changes caused by the deletion of VPS35L (EV column)." (PMID 37397996, 2023). "Therefore, our study is unique in providing the high-resolution cryo-EM structure of Retriever and uncovering the presence of cancer-associated mutations in VPS35L that impair Retriever assembly." (PMID 37397996, 2023).
congenital malformation syndrome (1 paper, 2023). "Prior to this study, only one pair of siblings with VPS35L pathogenic variants had been described, who presented with a severe form of congenital malformation syndrome." (PMID 36113987, 2023).
VPS35L also shares sentences with these, for which no sentence is quoted: hypercholesterolemia (1 paper); infection (1); intestinal lymphangiectasia (1); tumor (1); X-linked intellectual disability (1).